PRL (prolactin)
Diseases named in the same sentence as PRL in open-access papers (continued):
Sharing a sentence is not in itself a finding about the gene and the disease.
breast cancer (continued). "The influence of PRL on breast cancer remains a subject of debate: some studies have shown that prolactin levels are not significantly higher in patients with breast cancer than in control individuals." (PMID 40160874, 2025). "Thus, promoting PRL/PRLR pathway and/or blocking YAP-CCN2 can be exploited as differentiation therapeutic targets in breast cancer." (PMID 40157909, 2025). "Transgenic male mice that were treated with the mammary-selective, estrogen-insensitive promoter neu-related lipocalin (NRL), which drives PRL expression, and did not develop mammary tumors." (PMID 40160874, 2025). "The PRL-mediated activation of Nek3 contributes differentially to VAV2 signaling pathways involving Rac1 and signal transducer and activator of transcription 5 and implicates Nek3 during PRL-mediated actions in breast cancer." (PMID 40160874, 2025). "Further studies should address these limitations by evaluating breast cancer prevalence with and without aripiprazole use, ideally adjusting for prolactin concentrations." (PMID 40465597, 2025). "Also, together with prolactin (PRL) and 17β-estradiol (E2), SLC7A1 induces nitric oxide synthase to produce NO, thereby increasing breast cancer cell survival." (PMID 38705513, 2024). "Two hormones, prolactin (PRL) and estrogen (E2 for 17-β-estradiol), are absolutely required for normal mammary development and function, while their aberrant signaling is involved in breast cancer." (PMID 38933712, 2024). "There were no increased or decreased odds of breast cancer with exposure to prolactin-sparing antipsychotics of either 1–4 years (aOR = 1.17, 95%CI = 0.98–1.40) or ≥5 years (aOR = 0.99, 95%CI = 0.78–1.26)." (PMID 38687213, 2024). "Taken all together, these results demonstrated that mammary cancer cells acquired iron from the environment and the peptide hormone prolactin positively regulated iron uptake into cancer cells under normal circumstances (no extra iron presence)." (PMID 39201626, 2024). "Additionally, we have demonstrated that pTyr-PAK1, in response to PRL, regulates PTP-PEST-dependent FAK dephosphorylation, resulting in augmented breast cancer cell migration and invasion." (PMID 38660565, 2024). "Mitogen-activated protein kinase kinase (MEK)/extracellular signal-regulated kinase 1/2 (ERK1/2) along with PI3K/AKT pathways are jointly induced by PRL and EGF through their corresponding receptors, promoting the proliferation, survival, and metastasis of breast cancer cells." (PMID 37415164, 2023). "Moreover, downregulation of prolactin-mediated JAK2/STAT5A signaling by Mucuna pruriens, an ancient Indian medicinal plant enhanced cisplatin efficacy in the treatment of breast cancer cells." (PMID 38124049, 2023). "Resembling canine mammary tumors, PRL is largely not expressed while PRLR is expressed in human breast cancers." (PMID 37789381, 2023). "In addition to the well‐known effects on growth hormone and prolactin gene transcription, it has been demonstrated that CD163+ macrophages induce POU1F1 expression in breast cancer cells." (PMID 36373483, 2023). "While systemic prolactin does not seem to facilitate breast cancer growth, paracrine (as well as autocrine) prolactin stimulation is an important factor in mammary tumor formation." (PMID 37899389, 2023). "Here, in the present study, we identified the diosgenin to regulate the prolactin signaling pathway via the regulation of three genes i.e., STAT3, CYP17A1, and SRC which could avoid estrogen or progestogen receptor-mediated breast cancer progression." (PMID 36686654, 2022). "Experimental data showed that PRL receptors are expressed on breast cancer cells and that PRL does not induce breast carcinogenesis but has a positive effect on breast cancer progression in animals." (PMID 35000899, 2022). "Further, PRL also can be expressed by non-lactotrophs, including within the mammary gland, and by breast cancer cells themselves." (PMID 35784527, 2022).
breast cancer (continued). "Much of the discussion revolves around the extent of PRLR expression by the tumor parenchyma, including which breast cancer subtypes and which PRLR isoforms, and importantly, whether PRL fuels tumor aggression or fosters a more differentiated phenotype." (PMID 35784527, 2022). "Matrix stiffness switches prolactin signals from physiological STAT5 activation to protumorigenic Src/FAK and MMP activation and promotes the protumorigenic cross-talk between estrogen and prolactin in breast cancer cells." (PMID 35331296, 2022). "While the role of PRL as a differentiation factor in the mammary gland is well known, its role in breast cancer is still not fully characterized." (PMID 36157462, 2022). "The lack of anti-tumorigenic effects of blockers of PRLR suggests that the described pro-tumorigenic role of PRL in breast cancer BC is not of clinical value." (PMID 36157462, 2022). "On the other hand, PRL signaling targets the Bcl-6 protein and increases the expression of the transcription inhibitor ZEB1 to suppress the expression of E-cadherin and promote the EMT of breast cancer cells." (PMID 34034721, 2021). "G129R as an antagonist has the great potential to target the PRL/PRLR pathway since its binding to PRLR does not promote growth of breast cancer cells, instead, induces autophagy-related cell death." (PMID 34077462, 2021). "Interestingly, endogenous PRL induces ER responsiveness and enhances PRLR expression/transcription resulting in proliferation of breast cancer cells." (PMID 34572912, 2021). "Moreover, studies examining large cohorts of human breast cancer cases defined PRLR and PRL as markers of favorable clinicopathological parameters (tumor differentiation) and better patient survival outcomes." (PMID 33446633, 2021). "PRL is an important marker for HER2-tumor diagnosis and drug target for HER2+ breast cancer." (PMID 34099636, 2021). "PRL signaling through multiple pathways has been described for other cell lines, such as PI3K–AKT and STAT in Nb2 rat lymphoma cells, and STAT5, AKT, and ERK1/2 in T47D breast cancer cells." (PMID 33557010, 2021). "This approach ensured that all potential inhibitors of the PRL signaling cascade were identified, and that ‘hits’ recognized by the more sensitive, non-human lymphocytes also blocked PRL signaling in PRLR-expressing breast cancer cells." (PMID 34071395, 2021). "Prolactin through PRLR can activate both EGFR and HER2 downstream signaling pathways which in turn leads to activation of other oncogenic growth factors that promote growth, survival, and proliferation of breast cancer cells." (PMID 34572912, 2021). "Even a combined analysis of a serum panel of potential breast cancer markers, consisting of osteopontin, haptoglobin, haptoglobin, CA153, CEA, CA-125, prolactin, CA19-9, α-fetoprotein, leptin and migration inhibitory factor, is unable to predict the presence of early-stage breast cancer." (PMID 33803633, 2021). "We reasoned that a PRL-humanized PDX host strain should support engraftment and metastasis of luminal ER+ breast cancer while maintaining high engraftment rates of ER-negative breast cancer subtypes that may be less dependent on PRL." (PMID 34524841, 2021). "Altogether, the PRL/PRLR pathway being a major mammary terminal differentiation pathway, able to drive differentiation of breast cancer cells can thus be proposed as a potential therapeutic target in breast cancer." (PMID 33446633, 2021). "Multiple studies suggest that PRL and GH promotes breast cancer growth, leading to wide interest in PRLR/GHR as a potential target for breast cancer therapy." (PMID 33362552, 2020). "By placing the lipogenic master regulator SREBP-1c as one of the select target genes coregulated by STAT5 and PR-B, we can explain the PR-B isoform-specific regulatory actions on the cross-talk between prolactin and FASN signaling in luminal breast cancer cells." (PMID 33335078, 2020).
breast cancer (continued). "However, little is known about how prolactin and FASN signaling interact during breast cancer progression." (PMID 33335078, 2020). "Numerous studies have accepted the synergism between estrogen and PRL in the promotion of breast cancer and the ability of PRL to activate ERα in the absence of its natural ligand." (PMID 31507337, 2019). "Previous studies have found a negative cross-talk between PRL and TGFβ pathways in mammary and breast cancer cells." (PMID 30987013, 2019). "The data presented herein substantiate that the ECM is a potent determinant of the signaling cascades and outcomes of PRL actions in vivo, illuminating the apparent disparity between PRL exposure and activated STAT5 in the progression of clinical breast cancer." (PMID 28103936, 2017). "We and others have identified a synergy between prolactin and estrogen in the promotion of breast cancer, and the ability of prolactin to activate the estrogen receptor α (ERα) in the absence of an ERα ligand." (PMID 28422740, 2017). "PRL also induces Sonic Hedgehog (SHH) at the protein level in breast cancer cells, although the signal transduction pathway is not known." (PMID 27782069, 2016). "The role of PRL in breast cancer development/progression is not fully elucidated and further studies are clearly required to clarify its role." (PMID 27480353, 2016). "Additionally, PRL-induced pTyr-PAK1 is localized at small adhesion complexes at the cell periphery and regulates adhesion turnover in breast cancer cells, a process that is absolutely critical for cell motility." (PMID 27542844, 2016). "Although our understanding of the individual contributions of PRL and ECM characteristics to breast cancer progression is growing, the relative contributions of physical rigidity and collagen ligand density of the ECM that cooperate with PRL are poorly understood." (PMID 27344177, 2016). "On the other hand, the role of PRL in breast cancer development/progression is not fully elucidated." (PMID 27480353, 2016). "The effects of PRL on breast cancer and metastasis are not fully elucidated, and reports appear conflicting due to our lack of understanding of PRL biology." (PMID 27782069, 2016). "Indeed, we have previously shown that PRL, through PRLR/Jak2 signaling suppresses epithelial-mesenchymal-transition (EMT) and reduces the invasive properties of breast cancer cells." (PMID 27480353, 2016). "Together, our studies suggest that PRL signaling to FAK and SFKs may be useful targets in clinical aggressive ERα+ breast carcinomas." (PMID 27344177, 2016). "Understanding the means by which PRL–PRLR controls the interaction between cancer cells and the extracellular environment thereby influencing breast cancer cell motility may have clinical implications." (PMID 26733941, 2015). "The PRL-PRLR complex plays a role in mammary tumorigenesis, as shown, e.g., in human breast cancer." (PMID 26370564, 2015). "In contrast, other authors show that PRL does not have any effect on cell proliferation in the breast cancer cell lines MDA-MB-231, T-47D, MCF-7 and Hs578T." (PMID 26346346, 2015). "Compared to normal breast, Pit-1 expression is higher in breast tumors, increases cell proliferation, and regulates the expression of two breast cancer related hormones, growth hormone (GH) and prolactin (PRL), which are also involved in both MMP regulation and breast cancer metastasis." (PMID 25527274, 2014). "Understanding how PRL and other extracellular stimuli signal to key sites in the LKB1 promoter will provide important insight into the cellular responses that change during breast cancer progression." (PMID 24913037, 2014). "Indeed, others have shown that levels of the JAK2 phosphatase, PTP1B, are inversely correlated with nuclear levels of phosphorylated STAT5A and B in human breast cancer and that PTP1B suppressed the levels of PRL-induced phosphorylated STAT5A." (PMID 24913037, 2014).
breast cancer (continued). "We identified PRL-suppression of BCL6 transcript and protein based on this global transcript analysis of T47D xenotransplants tumors, and we reported a negative correlation between levels of BCL6 protein and Nuc-pYStat5 in clinical breast cancer specimens." (PMID 23758962, 2013). "More importantly, global profiling for PRL-modulated gene expression in human breast cancer in vivo has not been reported." (PMID 23758962, 2013). "The aim of this study was to expand our current knowledge about the influence of PRL on canine mammary tumorigenesis by evaluating PRLR expression in non-neoplastic canine mammary tissue and in benign and malignant mammary tumors by means of semi-quantitative real time (TaqMan) PCR." (PMID 22647582, 2012). "In primiparous mice, hyperthyroid did not result in increases in the incidence of mammary tumors in comparison to control mice when prolactin levels were maintained at normal levels." (PMID 22952723, 2012). "The levels of total LKB1 protein were modestly but significantly increased by 34 and 23% following stimulation with PRL in both MCF-7 and MDA-MB-231 breast cancer cells, respectively (1-fold vs. 1.34 ± 0.04-fold, p < 0.0001, and 1 vs. 1.23 ± 0.03-fold, p = 0.0002, respectively)." (PMID 21294903, 2011). "We have shown that treatment of breast cancer cells, particularly MDA-MB-231 cells, with PRL appreciably increases phosphorylation of the α subunit of AMPK at Thr172 beyond basal levels, which is linked with the phosphorylation and inactivation of one of its downstream effectors, ACC." (PMID 21294903, 2011). "We analysed PRL serum levels among 773 controls without breast cancer matched on age and residence to 776 invasive breast cancer cases with available pretreatment serum." (PMID 20736944, 2010). "Thus, we examined the effect of hormones and growth factors such as E2, EGF, prolactin and P4 on PAD2 expression in canine mammary epithelial cells using two canine mammary tumor-derived cell lines: CMT12 and CMT25 cells." (PMID 20668670, 2010). "The role of HSP90α downstream of prolactin helps explain the multiple effects of prolactin in normal cells and emphasises the significant contribution of prolactin-JAK2-STAT5 signal transduction to breast cancer." (PMID 19014541, 2008). "No further data are published on Δ1–9 in breast cancer, however it has been shown to induce apoptosis in prostate cancer cell lines by antagonising autocrine prolactin-mediated janus kinase 2 (JAK2)/STAT5A/B signalling." (PMID 18681966, 2008). "In contrast to a recent study of PRL and PRLR in relation to breast cancer, we observed no strongly significant associations with breast cancer risk." (PMID 18053149, 2007). "A total of 33 and 60 haplotype "tag" SNPs (tagSNPs) that allowed for high predictability (Rh2 ≥ 0.70) of the common haplotypes in PRL and PRLR, respectively, were then genotyped in a multiethnic breast cancer case-control study of 1,615 invasive breast cancer cases and 1,962 controls in the MEC." (PMID 18053149, 2007). "The role of other “reproductive” hormones such as prolactin, progesterone (when not combined with estrogen), and androgens thought important in stimulating mammary cancer in certain rodent models is less clear in breast cancer for women." (PMID 17805427, 2007). "Although circulating prolactin levels were dramatically reduced, no therapeutic benefit in the breast cancer patients was seen." (PMID 15213724, 2004). "Level of protein expression of CIS was not affected by serum starvation, suggesting that elevated CIS expression is intrinsic to these breast cancer lines, and does not require serum factors such as hGH, prolactin or colony-stimulating factors." (PMID 12888825, 2003). "Suppression of the secretion of prolactin, growth hormone and insulin-like growth factor 1 (IGF-1) might be important in the growth regulation and treatment of breast cancer." (PMID 9459155, 1998).
breast cancer (continued). "In the present study, we examined the possibility that aMT would also inhibit the stimulatory effects of the tumour-promoter prolactin (PRL) on MCF-7 and ZR75-1 human breast cancer cell (HBC) growth under 5% charcoal-stripped fetal bovine serum culture conditions." (PMID 8519656, 1995). "Basal prolactin (PRL) and total lactogenic hormone (TLH) levels were measured using a new microbioassay (BA) and conventional immunoradiometric assay (IRMA) in patients with breast cancer and compared to an age-matched control group." (PMID 1558804, 1992). "In addition to short-term fluctuations in estrogen and progesterone during ART, elevated levels of prolactin (PRL), HCG, gonadotropins, and other hormones may also affect the development of breast cancer." (PMID 40303287, 2025). "Notably, PRL demonstrates ligand-independent activation of ERα and stimulates parallel pathways including PI3K/AKT and MAPK, suggesting broad mechanistic involvement in breast cancer progression." (PMID 41370498, 2025). "While some studies have suggested that prolactin stimulates cellular proliferation, differentiation, and angiogenesis of breast cancer, other studies have not supported this hypothesis." (PMID 38554178, 2025). "Importantly, using CRISPR knockout of the PRLR in MCF7, HR+ breast cancer cells, further revealed that the negative relationship between PRL/PRLR pathway and YAP-CCN2 pathway is critical in suppressing luminal-to-basal stem-like lineage plasticity." (PMID 40157909, 2025). "Interestingly, when treated with PRL, MCF7 cells exhibited a rapid increase (within minutes) in the phosphorylation of YAP at Ser-127 suggesting Hippo as a downstream pathway of PRL signaling in breast cancer cells." (PMID 40157909, 2025). "Number of patients and breast cancer events for high prolactin-increasing antipsychotic users and non-prolactin-increasing antipsychotic users, we report population size, total exposure time, outcome events and minimal detectable risk ratio (MDRR) for the PS 1-1 matching analysis." (PMID 38595824, 2024). "Finally, elevated odds of breast cancer were also observed across all age groups at diagnosis for exposure to prolactin-increasing antipsychotics of ≥5 years, but not for exposure of 1–<5 years." (PMID 38687213, 2024). "However, the precise role of PRL-activated PAK1 in breast cancer and the respective signaling pathways affected is not well defined." (PMID 38660565, 2024). "While studies have emphasized the local/autocrine PRL and not the circulating endocrine PRL as contributing to mammary tumorigenesis and breast cancer development, however, other studies using large breast cancer patient data and cell lines provided different conclusions." (PMID 36157462, 2022). "Unlike circulating PRL, this locally elevated PRL does not disturb estrous cycling, enabling study of the interactions of PRL with ovarian hormones, of particular importance when assessing models of pre- and post-menopausal breast cancer." (PMID 35784527, 2022). "Prolactin in breast cancer cells could induce the phosphorylation of ERBB2/HER2, which in turn activates the downstream RAS/MEK/ERK pathway, leading to the proliferation of breast cancer." (PMID 36605402, 2022). "For example, “prolactin/ERK (extracellular signal-regulated kinase) signaling in breast cancer” was ranked ninth among GPSM1 statistically significant pathway analysis, and “mitogenic action of ESR1 (Estrogen Receptor 1) (membrane) in breast cancer” was ranked 15th for GPSM4." (PMID 34572330, 2021). "The incidence of breast cancer is higher in women with schizophrenia than in other women but this is probably due to confounding by indication (other aspects of schizophrenia and its sequelae being responsible for breast cancer, not high prolactin levels)." (PMID 33897500, 2021).